RNU6-1126P (RNA, U6 small nuclear 1126, pseudogene)
Gene: Small nuclear RNA gene on chromosome 7 (55,789,368 to 55,789,474, forward strand). Ensembl gene ENSG00000206729.
Homologues: Orthologues: chimpanzee U6 (99% identical), macaque U6 (95% identical). Paralogues in human: RNU6-1229P (91% identical), RNU6-973P (90% identical), RNU6-1060P (86% identical), RNU6-15P (86% identical), RNU6-26P (86% identical), RNU6-71P (86% identical), RNU6-1013P (85% identical), RNU6-1024P (85% identical), RNU6-19P (85% identical), RNU6-266P (85% identical), RNU6-47P (85% identical), RNU6-746P (85% identical), and 1289 more.